Y_RNA (Y RNA )
Gene: Miscellaneous RNA gene on chromosome X (21,872,707 to 21,872,808, forward strand). Ensembl gene ENSG00000206639.
Homologues: Orthologues: chimpanzee Y_RNA (99% identical), macaque Y_RNA (97% identical). Paralogues in human: Y_RNA (88% identical), RNY3 (87% identical), Y_RNA (87% identical), Y_RNA (86% identical), Y_RNA (85% identical), RNY3P1 (84% identical), RNY3P13 (84% identical), RNY3P16 (84% identical), RNY3P4 (84% identical), Y_RNA (84% identical), Y_RNA (83% identical), Y_RNA (82% identical), and 95 more.